GAS6 (growth arrest specific 6)
Diseases named in the same sentence as GAS6 in open-access papers (continued):
Sharing a sentence is not in itself a finding about the gene and the disease.
chronic kidney disease (5 papers, 2013 to 2022). Impairment of the renal function secondary to chronic kidney damage persisting for three or more months. "In chronic kidney disease patients, Gas6 levels were associated with renal disease and inversely related to renal function, suggesting that Gas6 levels may serve as a biomarker for disease stage." (PMID 26788441, 2016). "For example, elevated expression of MFGE8 was positively correlated with aortic stiffness in chronic kidney disease patients, and increased GAS6 levels in serum have been observed to correlate with elevated BP and age-related vascular remodeling in mice." (PMID 34929167, 2022). "Concerning the renal pathophysiology, it has been shown that not only Gas6 but also sMer and sAxl have a potential role as biomarkers in patients affected by chronic kidney disease (CKD)." (PMID 31485279, 2019). "In accordance with these findings, higher values of GAS6 have been reported in chronic renal failure." (PMID 23497733, 2013).
coronary artery disease (5 papers, 2013 to 2024). "Our results demonstrated that the plasma Gas6 levels were significantly lower in advanced coronary artery disease patients undergoing CABG than in control subjects and that plasma Gas6 levels were negatively correlated with fasting glucose, E-selectin, and VCAM-1 levels." (PMID 24236135, 2013). "Therefore, we hypothesized that the inflammatory effects of advanced coronary artery disease may be, at least in part, mediated through low Gas6 levels as well as reduced Gas6/Axl signaling, and consequently activated systemic immunity." (PMID 24236135, 2013). "The direct role of estrogen and Gas6 on coronary artery disease has not yet been deciphered and more investigation is needed about the tissue-specific regulation of Gas6, PS, and the TAM system via estrogen and androgen response elements." (PMID 39684449, 2024). "Finally, we showed a negative association of GAS6 and ATF3 expression with the risk of major adverse cardiac events in patients with ischemic heart disease." (PMID 39195894, 2024). "Our data first represented that the circulating Gas6 levels were associated with the clinical predicted rate of operative mortality in CABG patients and that it could be used as a nonconventional risk factor in advanced coronary artery disease." (PMID 24236135, 2013).
endometriosis (5 papers, 2008 to 2025). The growth of functional endometrial tissue in anatomic sites outside the uterine body. "Recent studies have revealed its association with the pathophysiology of endometriosis and identified GAS6 as one of the hub genes and a biomarker candidate." (PMID 40943271, 2025). "Recently, GAS6 was identified in a mouse model of endometriosis when single-cell transcriptomics of endometriosis-associated macrophages was performed." (PMID 40943271, 2025). "Therefore, the PCB126/AXL/GAS6/ESR2 axis represents a key mechanism underlying the induction of endometriosis-associated DNA methylation via DNMT3A." (PMID 41054802, 2025). "Therefore, the PCB126/AXL/GAS6/ERβ axis represents a key mechanism underlying the induction of endometriosis-associated DNA methylation via DNMT3A." (PMID 40951281, 2025). "Future studies need to clarify whether GAS6 contributes directly to the mechanism of endometriosis-associated pain or primarily reflects systemic inflammation." (PMID 40943271, 2025). "This is the first study to investigate GAS6 as a potential diagnostic biomarker for endometriosis." (PMID 40943271, 2025). "Therefore, it is possible that overexpression of AXL and GAS6 is a main cause for the activation of the PI3K-Akt pathway in endometriosis." (PMID 19055724, 2008). "Its important role in the regulation of immune system cells suggests that GAS6 may also play a role in benign diseases associated with an impaired immune system, such as systemic lupus erythematosus and venous thromboembolic disease, and also in endometriosis." (PMID 40943271, 2025). "Published data showing an important role of GAS6 in the pathophysiology of endometriosis and data reporting its potential as a diagnostic biomarker prompted us to investigate the levels of GAS6 in plasma samples from patients with endometriosis." (PMID 40943271, 2025). "Collectively, our study identifies the PCB126/AXL/GAS6/ERβ/DNMT3A axis as a key integrator of endocrine-disrupting chemical (EDC)-mediated endometriosis progression." (PMID 40951281, 2025). "Our results indicate that GAS6 is increased in patients with endometriosis, but it cannot serve as a biomarker candidate." (PMID 40943271, 2025). "Our case–control study included 284 patients and showed that plasma levels of GAS6 are significantly higher in patients with endometriosis compared to control patients." (PMID 40943271, 2025). "We found statistically significantly higher concentrations of GAS6 in plasma samples from patients with different types of endometriosis compared to control patients (p = 0.015)." (PMID 40943271, 2025). "The hypothesis that GAS6 can be found in higher concentrations in blood samples from patients with endometriosis compared to control patients was confirmed." (PMID 40943271, 2025). "Although our results do not support the use of plasma GAS6 as a diagnostic biomarker for endometriosis, we observed that GAS6 levels are associated with pain symptoms (dysmenorrhoea and dyspareunia)." (PMID 40943271, 2025). "We investigated GAS6 as a candidate biomarker for the diagnosis of endometriosis." (PMID 40943271, 2025). "As the PI3K-Akt pathway is involved in cell survival, proliferation, and migration, its activation through GAS6/AXL may be a common central biological event during the pathogenesis of endometriosis." (PMID 19055724, 2008). "Moreover, these pathways have been shown to enhance the transcriptional activity of ERβ Therefore, we propose that kinases activated by the PCB126/AXL/GAS6 axis may, in turn, activate ERβ to promote endometriosis progression." (PMID 40951281, 2025). "Therefore, we hypothesised that GAS6 levels are elevated in patients with different types of endometriosis." (PMID 40943271, 2025). "The PCB126/AXL/GAS6/ERβ/DNMT3A axis provides a critical clue for understanding how EDCs may epigenetically drive the formation of an inflammatory-immune microenvironment that promotes endometriosis progression." (PMID 40951281, 2025).
endometriosis (continued). "ESR2 is a well-established driver of endometriosis, and PCB126 enhances ESR2 activity through the AXL/GAS6 signaling axis." (PMID 41054802, 2025). "Collectively, our study demonstrated that exposure to PCB126 indirectly upregulated Dnmt3a through the activation of the AXL/GAS6/ESR2 axis, leading to dysregulation of epigenomic regulation in the endometrium and promoting the progression of endometriosis." (PMID 41054802, 2025). "ERβ is a well-established driver of endometriosis, and PCB126 enhances ERβ activity through the AXL/GAS6 signaling axis." (PMID 40951281, 2025). "The PPI network analysis reveals hub genes, including BCL2, CCNA2, CDK7, EGF, GAS6, MAP3K7, and TAB2, which emerge as pivotal players in endometriosis progression." (PMID 39108650, 2024). "It is possible that GAS6 plays a role in the pathophysiology of the different types of endometriosis, but the plasma concentrations do not reflect the tissue concentrations." (PMID 40943271, 2025). "From the results of this study, we conclude that GAS6 is not a biomarker candidate for endometriosis." (PMID 40943271, 2025). "Plasma levels are known to reflect systemic changes as plasma circulates in the body, so elevated GAS6 levels may indicate other systemic processes rather than specific endometriosis." (PMID 40943271, 2025).
Hyperglycemia (5 papers, 2014 to 2023). An increased concentration of glucose in the blood. "CellChat predicted that hyperglycemia-induced GAS6 signaling was mediated by ligand GAS6 and both two receptors, Ligand GAS6 was up-regulated in microglia and amacrine, whereas the receptors were up-regulated in microglia." (PMID 34434927, 2021). "Collectively, these findings indicate that the correlation between GAS6 and systemic inflammation could be significantly affected by ageing, gender, and hyperglycemia." (PMID 25954309, 2015). "In addition, hyperglycemia might affect the Gas6 (growth arrest-specific protein 6)/Axl/Akt signaling pathway in human microvascular endothel cells, as in observational and in vitro studies Gas6 and Gas6/Axl expression was found to be downregulated by increased glucose concentrations." (PMID 25281032, 2014). "However, the role of Gas6/Axl and downstream signaling in the context of hyperglycemia and endothelial functions has not been explored." (PMID 24572151, 2014).
myeloma (5 papers, 2019 to 2025). "In the study population, we found that HO-1 was highly expressed in CD138+ primary myeloma cells, which was positively associated with Gas6 expression and Gas6 plasma levels in MM patients." (PMID 32298237, 2020). "In this study, our main findings demonstrate that HO-1 is associated with increased Gas6 expression in MM patients, and inhibition of HO-1 enhances sensitivity to bortezomib in myeloma cells via suppressing Gas6 expression and secretion." (PMID 32298237, 2020). "Blockade of MERTK on MM cells or pharmacologic targeting of GAS6 reduces myeloma burden and increases survival of mice bearing an orthotopic myeloma model." (PMID 35967396, 2022). "Collectively, these results suggest that HO-1 inhibition enhance sensitivity to bortezomib in myeloma cells via suppressing Gas6 production." (PMID 32298237, 2020). "The findings that HO-1 inhibition suppressed Gas6 expression and secretion were observed in myeloma cell." (PMID 32298237, 2020). "Beside, we observed that both trametinib and NSC74859 markedly decreased the production of soluble Gas6 in culture medium from myeloma cells." (PMID 32298237, 2020). "We observed that Gas6 was greatly increased in CD138+ myeloma cells from stage I to stage III MM patients compared with healthy controls." (PMID 32298237, 2020). "GAS6 promoted survival and proliferation of myeloma cells and protected them against bortezomib-induced apoptosis." (PMID 31694201, 2019). "All these data indicate that MERTK is the most important TAM receptor in proliferating myeloma cells and that GAS6/MERTK signaling regulates myeloma cell survival and resistance." (PMID 31694201, 2019). "Additionally, downregulation of MERTK expression or therapeutic blockade of GAS6 by Warfarin resulted in reduced disease burden and prolonged overall survival in a systemic myeloma mouse model." (PMID 38203403, 2023). "Additionally, we aimed at investigating the molecular mechanism how HO-1 regulates Gas6 in bortezomib-resistant myeloma cells." (PMID 32298237, 2020). "The authors proved that GAS6, secreted by bone marrow stromal cells, activated AXL and MERTK signaling, which promoted MICA expression in myeloma cells via the NF-kB pathway." (PMID 38203403, 2023). "GAS6 and MERTK expression were found to be upregulated in malignant bone marrow PC of myeloma patients compared with healthy donor samples." (PMID 38203403, 2023). "Our results showed that HO-1 enhanced autocrine action of Gas6 in MM cell lines and CD138+ myeloma cells, but the function of HO-1 in Gas6 secretion by bone marrow stroma cells is unclear." (PMID 32298237, 2020). "The number of GAS6+ and MERTK+ bone marrow plasma cells (BMPCs) were significantly increased in myeloma patients compared to healthy controls; whereas AXL and TYRO3 were mainly undetectable in BMPCs of both groups and also in human myeloma cell lines." (PMID 31694201, 2019).
Thromboembolism (5 papers, 2011 to 2025). The formation of a blood clot inside a blood vessel that subsequently travels through the blood stream from the site where it formed to another location in the body, generally leading to vascular occlusion at the distant site. "Furthermore, the potential risk of increasing Gas6 carboxylation with vitamin K and its effects on thromboembolism and cancer cell spread also needs to be considered." (PMID 39861478, 2025). "Therefore, GAS6 deficiency protects from thrombosis in mouse models due to defective endothelial activation and platelet aggregation and higher circulating GAS6 levels have been associated to thromboembolism." (PMID 32998369, 2020). "Gas6 has been shown to promote growth and therapy resistance among different types of cancer as well as thromboembolism." (PMID 34836355, 2021). "Then, the concern is again the counterproductive effect of a potential improvement of Gas6 activity by increased carboxylation in cancer and thromboembolism." (PMID 34836355, 2021).
acute lung injury (4 papers, 2019 to 2025). A condition of lung damage that is characterized by bilateral pulmonary infiltrates (pulmonary edema) rich in neutrophils, and in the absence of clinical heart failure. "GAS6, IL-6 and IL-8 concentrations are increased in septic patients who develop acute lung injury (ALI;41." (PMID 34344929, 2021). "This study investigates whether Gas6-induced AIM suppresses acute lung injury (ALI) in mice by modulating key inflammatory pathways, including inflammasome activation, autophagy, reactive oxygen species (ROS) generation, and efferocytosis." (PMID 40034700, 2025). "The role of Gas6/Axl signaling in ischemia-reperfusion-induced acute lung injury (IR-ALI) has not been explored previously." (PMID 31318922, 2019).
colitis (4 papers, 2017 to 2023). Inflammation of the colon. "Interestingly, Gas6−/− mice exhibited more severe DSS-induced colitis." (PMID 38029085, 2023). "Paradoxically, experimental evidence has demonstrated that the marked susceptibility to experimentally induced colitis observed in mutant mice lacking Gas6 as well as Axl and Mer correlates with increased incidence of colon cancer, resulting in larger tumors and reduced overall survival." (PMID 31247991, 2019). "The mRNA expression of Axl and its ligand, Gas6 was remarkably increased in the small intestine, colon, and mesenteric lymph node in the DSS-induced colitis mice." (PMID 37005456, 2023). "Immunohistochemical analysis revealed that the expression of Axl and Gas6 was upregulated in the colon and small intestine of the DSS-induced colitis mice (brown colored areas in the images)." (PMID 37005456, 2023).
colon cancer (4 papers, 2016 to 2019). "For instance, in a syngeneic murine colon cancer model, circulating leukocytes and tissue-resident macrophages expressed minimal GAS6, but GAS6 was dramatically upregulated in tumor-associated macrophages." (PMID 30501104, 2018). "This study provides evidence for the role of the Gas6/TAM receptor pathway, especially the Mer and Tyro3 receptors in human colon cancer." (PMID 27486820, 2016).
demyelination (4 papers, 2011 to 2025). "In an acute demyelination mouse model, activated astrocytes express multiple ligands, including Cx3cl1, Csf1, Il34, and Gas6, which act on both homeostatic and activated microglia, thereby potentially mediating microglial activation, recruitment, and enhancing their phagocytic activity." (PMID 40292254, 2025). "Moreover, Gas6 has been shown to be capable of boosting remyelination in a cuprizone-induced demyelination model." (PMID 32722558, 2020). "We initially investigated whether the absence of Gas6 affects the rate or level of remyelination following cuprizone-induced demyelination." (PMID 21423702, 2011).
Insulin resistance (4 papers, 2014 to 2024). Increased resistance towards insulin, that is, diminished effectiveness of insulin in reducing blood glucose levels. "However, elevated levels of Gas6 have been associated with insulin resistance." (PMID 39684449, 2024). "In this study, a strong association between GAS6 and AXL polymorphisms with body adiposity, systemic inflammation, and insulin resistance was identified among boys." (PMID 24696684, 2014). "In conclusion, we indicate an association between the GAS6 and AXL polymorphisms with adiposity, circulating inflammatory markers, and insulin resistance of adolescents, especially in boys." (PMID 24696684, 2014). "The present study was designed to explore the effects of GAS6 and AXL gene polymorphisms on adiposity, systemic inflammation, and insulin resistance in adolescents." (PMID 24696684, 2014). "In conclusion, GAS6 and AXL polymorphisms are associated with adiposity, systemic inflammation, and insulin resistance in adolescents, especially in boys." (PMID 24696684, 2014). "However, the synergy of Gas6 and estrogen effects on insulin resistance is debated." (PMID 39684449, 2024). "In order to address this issue, we conducted a community-based study to determine whether common variations in the GAS6 and AXL genes correlate with adiposity, systemic inflammation, insulin resistance among adolescents." (PMID 24696684, 2014).
intestinal cancer (4 papers, 2017 to 2025). "As a γ-carboxyglutamic acid domain-containing protein that can engender platelet-mediated thrombosis, GAS6 has been implicated to promote cancer cell proliferation in intestinal cancer cell lines." (PMID 37958942, 2023). "Gas6 may decrease the immunological response of colonic mesenchymal cells, which could explain its suppressive action on intestinal cancers." (PMID 39748782, 2025). "Additionally, the Gas6/TAM inhibitory mechanism in intestinal cancers has been steadily identified." (PMID 39748782, 2025).
lymph node metastases (4 papers, 2008 to 2016). "Gas6 mRNA expression was inversely associated with the presence of lymph node metastases." (PMID 18283315, 2008). "In concordance with these results, our data showed that elevated Gas6 level was related to lymph node metastases, TNM stage, prognosis, and so on." (PMID 26207647, 2015). "Similarly, Gas6 was higher expressed in patients with lymph node metastases, while Mer expression showed a trend towards higher expression in primary tumors from patients suffering liver metastasis (p = 0.1)." (PMID 27486820, 2016).
osteoarthritis (4 papers, 2017 to 2023). A noninflammatory degenerative joint disease occurring chiefly in older persons, characterized by degeneration of the articular cartilage, hypertrophy of bone at the margins and changes in the synovial membrane. "GAS6 restored osteoarthritis (OA) cartilage loss and decreased apoptotic cell accumulation." (PMID 37144868, 2023). "The activation of the AMPK/Gas6/MerTK/SOCS3 signal pathway by ozone also provides new theoretical evidence for ozone treatment of osteoarthritis." (PMID 38066599, 2023). "Thus, in this study, we investigated the effect of Gas6 exposure on the inflammatory response of synovial fibroblasts obtained from patients with osteoarthritis." (PMID 37242486, 2023).
osteoporosis (4 papers, 2020 to 2024). A condition of reduced bone mass, with decreased cortical thickness and a decrease in the number and size of the trabeculae of cancellous bone (but normal chemical composition), resulting in increased fracture incidence. "Among these, GAS6, SPP24, RAB7A, and TSP are known to play a role in fibroblast proliferation, angiogenesis, and immune response and may offer insight into the mechanism of osteoporosis." (PMID 39336514, 2024).
renal carcinoma (4 papers, 2016 to 2023). A carcinoma arising from the epithelium of the renal parenchyma or the renal pelvis. "With high binding affinity to GAS6, its potential efficacy in inhibit tumor growth, invasion and metastasis has been extensively studied in ovarian, pancreatic, breast and renal cancer cancers." (PMID 36980768, 2023). "An additional field in which Gas6 shows potential interest is renal cancer, more specifically in clear cell renal carcinoma (CCRC), the most common type of renal cell carcinoma." (PMID 30934817, 2019). "Gas6 has a critical role in the development of multiple types of cancers, including pancreatic, prostate, oral, ovarian and renal cancers." (PMID 28333143, 2017).